HLA-DRB6 (major histocompatibility complex, class II, DR beta 6 (pseudogene))
Gene: Transcribed unprocessed pseudogene on chromosome 6 (32,553,046 to 32,558,186, reverse strand). Ensembl gene ENSG00000229391.
Diseases named in the same sentence as HLA-DRB6 in open-access papers:
HLA-DRB6 is named in the same sentence as 21 diseases in open-access papers, as found by Europe PMC text mining. Sharing a sentence is not in itself a finding about the gene and the disease. The quoted sentences say what the papers report.
autoimmune disease (2 papers, 2020 to 2024). A disorder resulting from loss of function or tissue destruction of an organ or multiple organs, arising from humoral or cellular immune responses of the individual to their own tissue constituents. "In our results, we also find a variety of pseudogenes (HLA-DRB6, CYP21A1P, PSORS1C3) that have a significant effect on the risk of autoimmune diseases." (PMID 39590325, 2024). "Within this chromosome, HLA-DQA1, HLA-DRB6, HLA-DQA2, HLA-DQB2, HLA-DRB1, and HLA-DQB1-AS1 were notable for having causal associations among several autoimmune diseases." (PMID 39590325, 2024).
sarcopenia (2 papers, 2020 to 2025). Progressive decline in muscle mass due to aging which results in decreased functional capacity of muscles. "MMP24‐AS1, HLA‐DRB6, HLA‐DQA2, DDX42, BAG6, NUSAP1, LINC00940, NME1‐NME2 and AS3MT in the amygdala region showed detrimental effect on all the five sarcopenia‐related traits, whereas HLA‐DRB1, HLA‐DQB1‐AS1 and C6ORF3 showed protective effect (p < 0.05)." (PMID 39535371, 2025). "The over‐expression of nine genes (MMP24‐AS1, HLA‐DRB6, HLA‐DQA2, DDX42, BAG6, NUSAP1, LINC00940, NME1‐NME2 and AS3MT) in the amygdala region showing detrimental effect on all the five sarcopenia‐related traits, whereas three genes (HLA‐DRB1, HLA‐DQB1‐AS1 and C6ORF3) showing protective effect." (PMID 39535371, 2025).
allergic disease (1 paper, 2020). An immune response that occurs following re-exposure to an innocuous antigen, and that requires the presence of existing antibodies against that antigen. "For example, 4 genes of C2CD2, HLA-DRB6, LPCAT2, and HLA-DQB1 were associated with TB risk, and RUNX showed association with asthma or allergic disease risk." (PMID 33051402, 2020).
cervical cancer (1 paper, 2021). A primary or metastatic malignant neoplasm involving the cervix. "In a recent study, HLA-DRB6 was found to be upregulated among cervical cancer tissues and cell line data." (PMID 34834481, 2021).
colon cancer (1 paper, 2024). "Notably, relationships between VSIG4, HLA-DRA, and HLA-DRB6 were observed in this study, indicating that VSIG4 may mediate the expression of HLA-DR family genes through antigen presentation and be involved in the immune activation mechanism of MSI colon cancer." (PMID 39726813, 2024).
psoriasis (1 paper, 2025). An autoimmune condition characterized by red, well-delineated plaques with silvery scales that are usually on the extensor surfaces and scalp. "Our database search revealed that research on PSORS1C3, as its name suggests, primarily focuses on its involvement in psoriasis, while studies on HLA‐DRB6 have stagnated since the 1990s." (PMID 40099350, 2025).
squamous carcinoma (1 paper, 2021). "DDR-deficient types had lower expressions of STING1 (p = 0.01), CD28 (p = 0.020), HLA-DRB6 (p = 0.014) in adenocarcinoma, lower TNFRSF4 (p = 0.017), and TGFB1 expressions (p = 0.033) in squamous carcinoma, and higher CD40 (p = 0.012) and TNFRSF14 expressions (p = 0.022) in SCLC." (PMID 34604048, 2021).
tumor (7 papers, 2013 to 2024). "Heatmap indicated that NCF1C, HLA-DRB6, HLA-DPB2, HLA-J, HLA-H, HLA-L and RPL13AP20 displayed high expressions in the low-risk group, and thus were categorized as tumor-suppressor pseudogenes in the current study." (PMID 33378744, 2020). "Interestingly, our study showed strong association of five HLA genes (including HLA-DMA, HLA-DMB, HLA-DOA, HLA-DRB6 and HLA-E) with delayed tumor recurrence in both cohorts." (PMID 34834481, 2021). "Additionally, a decreased expression of HLA-DRB6 was also reported in HCC patients compared to non-tumor liver tissues." (PMID 34834481, 2021).
HLA-DRB6 also shares sentences with these, for which no sentence is quoted: adenocarcinoma (1 paper); asthma (1); autism (1); breast carcinoma (1); cancer (1); cervix tumors (1); Hypertension (1); rheumatoid arthritis (1); sarcoidosis (1); Sepsis (1); skin atrophy (1); systemic sclerosis (1); type 1 diabetes mellitus (1).